TRIM38 (tripartite motif containing 38)
Diseases named in the same sentence as TRIM38 in open-access papers (continued):
Sharing a sentence is not in itself a finding about the gene and the disease.
nonalcoholic steatohepatitis (1 paper, 2023). "Mechanically, RNA-Seq analysis demonstrated that TRIM38 ameliorated nonalcoholic steatohepatitis progression by attenuating the activation of MAPK signaling pathway." (PMID 37116711, 2023).
tumor (8 papers, 2021 to 2025). "To further investigate the potential mechanisms of tumor progression mediated by TRIM38 deficiency, we conducted the Gene Set Enrichment Analysis (GSEA) in TCGA-BLCA dataset based on the expression data matrix." (PMID 34906161, 2021). "Lastly, the tumor xenografts models were further established and BAY-876 was also effective to inhibit the growth of tumors derived from TRIM38-deficient cells, as indicated by the tumor volumes and tumor weight." (PMID 34906161, 2021). "By analyzing the clinicopathological characteristics, we found that TRIM38 mRNA expression was negatively correlated to tumor size, depth of invasion, liver metastasis as well as tumor stage." (PMID 40047371, 2025). "Xenograft tumor models demonstrated that TRIM38 silence promoted tumor growth, as evidenced by increased tumor volume, tumor weight, and Ki‐67 level compared to the control group, while TRIM38 overexpression had the opposite effect." (PMID 40047371, 2025). "In vivo, the xenograft model demonstrated that downregulation of CCT6A significantly inhibited tumor growth and negated the influence of TRIM38 knockdown on tumor progression." (PMID 40047371, 2025). "Clinical analysis revealed that decreased TRIM38 was correlated with tumor progression and poor prognosis." (PMID 40047371, 2025). "Some genes (TRIM22/TRIM38/TRIM5/TRIM59) are expressed lower in tumor cells than in other cell types." (PMID 35928444, 2022). "The underlying relationships between TRIM38 and immune infiltrations in BLCA tumor microenvironment (TME) were still unclear." (PMID 34906161, 2021). "TRIM38 was reported to regulate immunity, inflammatory responses or apoptosis, but its roles in tumor progression remain inconclusive." (PMID 34906161, 2021). "Our results suggested that TRIM38 plays a tumor suppressive role in BLCA pathogenesis and TRIM38/GLUT1 axis is a therapeutic vulnerability for clinical treatment, which possessing great translational significance." (PMID 34906161, 2021). "We found that TRIM38 protein levels were significantly lower in tumor samples than normal tissues via immunohistochemistry (IHC)." (PMID 34906161, 2021). "To further reveal the role of TRIM38 in CRC, we measured the TRIM38 mRNA levels in 200 pairs of tumor tissues and adjacent normal tissues from CRC patients by qRT‐PCR, revealing a significant downregulation of TRIM38 in CRC, consistent with findings from the TCGA and GEO databases." (PMID 40047371, 2025). "Moreover, TRIM38 functions as a tumor suppressor by inhibiting cell proliferation, metastasis, and AOM/DSS‐induced tumorigenesis in CRC cells." (PMID 40047371, 2025). "Given that we have already found that low TRIM38 depended on accumulated GLUT1 to drive tumor progression, we thus considered whether GLUT1 inhibitor could be effective to suppress tumour growth in TRIM38low BLCA." (PMID 34906161, 2021). "The mRNA levels of TRIM38 were also significantly down-regulated in tumor samples." (PMID 34906161, 2021). "Collectively, these findings indicated that TRIM38 might be a tumor suppressor in BLCA that deserves to be further investigated." (PMID 34906161, 2021). "Functional assays further confirmed that TRIM38 could restrict tumor growth and TRIM38 inhibition resulted in enhanced cell proliferation ability, migration efficiency and self-renewal potentiality." (PMID 34906161, 2021). "Whether there existed other downstream targets of TRIM38 in BLCA that account for tumor progression is interesting to be thoroughly figured out." (PMID 34906161, 2021). "Several genes associated with the GO category of “Regulation of viral entry into host cells,” TRIM5, TRIM21, TRIM22, and TRIM38 were over-expressed in GBM compared to ODG and non-tumor samples." (PMID 35896929, 2023). "To further confirm the clinical significance of TRIM38 in BLCA, we collected totally 30 tumor samples with matched normal tissues from the department of urology, Shanghai Ruijin Hospital." (PMID 34906161, 2021).
tumor (continued). "In the study, our team identified for the first time that TRIM38 is a tumor suppressor in BLCA pathogenesis and demonstrated the biological roles of TRIM38 in BLCA through in vitro and in vivo experiments." (PMID 34906161, 2021). "The representative IHC images of normal/tumor and low/high grade tissues from HPA revealed that the degree of staining intensity of CD96, DDB1, IP6K2, PDCL3, TRIM38, and KCNJ15 were in correspondence with our predictions of coefficient." (PMID 34268106, 2021). "Because OC is primarily a tumor of epithelial origin, the expression of TRIM proteins was analyzed in epithelial cells, and the eight most highly expressed genes (TRIM28, TRIM27, TRIM33, TRIM38, TRIM47, TRIM56, TRIM8, and TRIM24) were determined." (PMID 38881325, 2024).
infection (7 papers, 2012 to 2025). The state of being infected such as from the introduction of a foreign agent such as serum, vaccine, antigenic substance or organism. "The growth curve of ZIKV indicated that TRIM38 overexpression significantly suppressed ZIKV replication from 24 to 48 h post-infection, with the most pronounced inhibitory effect observed at 48 hpi." (PMID 40006954, 2025). "Growth curves of ZIKV showed that the antiviral efficacy of TRIM38 was stronger during the later stages of infection than during the early stages." (PMID 40006954, 2025). "The expression levels of TBK1 and IRF3 were significantly increased in TRIM38 overexpressing cells after infection with ZIKV." (PMID 40006954, 2025). "During the later stages of infection, TRIM38 negatively regulates the TLR3/4 signaling, consequently suppressing the production of proinflammatory cytokines including TNF-α, IL-1β, and IL-6." (PMID 40006954, 2025). "Exposure to poly(I:C) led to a 2–3 fold increase in IFN-β and ISG56 mRNA expression 4 h post-infection in the TRIM38 knockdown cells compared to control cells." (PMID 23056470, 2012). "We propose that the interaction between TRIM38 and ZIKV NS3 protein exerts a more significant direct antiviral effect on ZIKV replication post-infection." (PMID 40006954, 2025). "We found that tripartite motif-containing proteins (TRIMs) including TRIM38, TRIM21, and TRIM14 were significantly enriched during infection with mosquito-borne (West Nile virus strain Kunjin and Zika virus (ZIKV)) and tick-borne (Langat virus (LGTV)) flaviviruses." (PMID 40431659, 2025). "However, TRIM38, which was only enriched in the nucleus by ORF6 after IFN treatment, was only marginally enriched in the nucleus after infection." (PMID 36007063, 2022).
cancer (3 papers, 2021 to 2025). A tumor composed of atypical neoplastic, often pleomorphic cells that invade other tissues. "On the other hand, TRIM38 causes abnormal activation of NF-κB pathway thereby inhibiting cancer." (PMID 34268106, 2021). "Taken together, these results revealed that TRIM38 is reduced in CRC and might play an anti‐cancer role in CRC." (PMID 40047371, 2025).
bacterial infections (1 paper, 2025). "The crucial role of Trim38 during bacterial infections is reflected in its regulation of the NF-κB signaling pathway." (PMID 40362389, 2025).
TRIM38 also shares sentences with these, for which no sentence is quoted: AIDS (1 paper); bladder tumor (1); brain diseases (1); diabetes (1); Insulin resistance (1); liver inflammation (1); lung carcinoma (1); prediabetes (1); sarcopenia (1); steatosis (1).